TMPRSS2 (transmembrane serine protease 2)
Diseases named in the same sentence as TMPRSS2 in open-access papers (continued):
Sharing a sentence is not in itself a finding about the gene and the disease.
lung carcinoma (continued). "Compared to normal people, we found that smoking and lung cancer increase the risk for COVID-19 infection due to a higher expression of ACE2 and TMPRSS2 in lung cells." (PMID 32973879, 2020). "Then, we evaluated the expression of ACE2 and TMPRSS2 in lung cancer patients through IHC staining, and markedly upregulated expression of the two genes was presented in lung cancer patients compared with normal samples." (PMID 33195212, 2020). "Data using the lung cancer cell line, Calu-3 cells transfected with SARS-CoV as well as lung cancer samples showed less elevated TMPRSS2 expression than ACE-2 expression, which was highly expressed." (PMID 32764454, 2020). "Expression levels of TMPRSS2 were assessed by RT-PCR in COVID 19 HNSCC patient as well as in five lung cancer patient samples resected from 2011 to 2014 respectively." (PMID 32967703, 2020). "The study suggests that TMPRSS2 downregulation may impair immune surveillance in lung cancer patients." (PMID 40145441, 2025). "Also, in vitro studies of A549 human lung cancer cells have shown that 24 h of testosterone treatment results in the upregulation of the TMPRSS2 gene, upregulating TMPRSS2 protein on the cell surface." (PMID 39449074, 2024). "To determine whether the level of TMPRSS2 may impact tumorigenicity in lung cancer cells, we examined the effect of stable depletion of TMPRSS2 on anchorage‐independent growth of H1975 cells." (PMID 36975376, 2023). "Consequently, our research also offers novel insights into TMPRSS2’s possible role in tumor immunology as well as its potential use as a biomarker and novel therapeutic target for lung cancer." (PMID 36992839, 2023). "To determine whether the expression level of TMPRSS2 is increased in lung cancer cells, we examined the endogenous protein level of TMPRSS2 in four established lung cancer cell lines and two normal lung fibroblasts by Western blotting." (PMID 36975376, 2023). "In this study, to gain a deeper understanding of how TMPRSS2 affects lung cancer, especially LUAD and LUSC, we used various types of bioinformatic approaches and IHC to determine the relationships between TMPRSS2 expression, methylation level, and OS, clinical parameters, biological process." (PMID 36992839, 2023). "According to the methylation analysis here, the level of TMPRSS2 may fluctuate throughout the course of lung cancer." (PMID 36992839, 2023). "Therefore, TMPRSS2‐mediated signaling is clearly involved in promoting tumor growth in lung cancers." (PMID 36975376, 2023). "Finally, the role of TMPRSS2 expression in lung cancer was examined in tumor specimens from patients." (PMID 36975376, 2023). "We used the TCIA database to investigate whether TMPRSS2 influences the response of patients with lung cancer to anti-PD-1 immunotherapy." (PMID 36992839, 2023). "Interestingly, increased TMPRSS2 expression was positively correlated with advanced stages of lung cancer, supporting our finding that TMPRSS2 plays an important role in tumor progression of lung cancer." (PMID 36975376, 2023). "Additionally, we also found a significant decrease of TMPRSS2 in tumor tissues of patients with lung cancer." (PMID 36992839, 2023). "To determine whether TMPRSS2 affects lung cancer cell tumorigenesis in vivo, we performed a xenotransplantation assay in nude mice." (PMID 36975376, 2023). "However, the biological function of TMPRSS2 in lung cancer is unclear, and the current research results are inconsistent." (PMID 36975376, 2023). "Furthermore, the cancer immunome atlas (TCIA) database was used to predict the relationship between the expression of TMPRSS2 and response to programmed cell death protein 1 (PD-1) blocker immunotherapy in lung cancer patients." (PMID 36992839, 2023). "Moreover, the expression level of TMPRSS2 and PD-1 and PD-L1 demonstrated different correlation patterns in the tumor tissue of lung cancer (AA, AE, AG)." (PMID 36992839, 2023).
lung carcinoma (continued). "This study provides an overview of TMPRSS2 expression and lung cancer." (PMID 36992839, 2023). "Hence, we compared TMPRSS2 and AR basal protein expressions in two lung cancer cell lines (A549 and Calu-3) versus two PCa cells lines (VCaP and LNCaP) by Western blot." (PMID 36834705, 2023). "HR below 1 implies that TMPRSS2 expression has a protective effect on patients with lung cancer." (PMID 36992839, 2023). "Low TMPRSS2 mRNA expression also correlated with poor outcome in lung cancer patients." (PMID 35017320, 2022). "Moreover, we compared TMPRSS2 expression in lung cancer using the TCGA dataset, and the results demonstrated that TMPRSS2 expression was significantly downregulated in lung cancer tissues." (PMID 35017320, 2022). "TMPRSS2 mRNA and protein expression was significantly reduced in lung cancer." (PMID 35017320, 2022). "Additionally, there were significant associations between TMPRSS2 expression and poor OS in AJCC stage T-1 and stage M-0 lung cancer patients." (PMID 35017320, 2022). "Intriguingly, reduced TMPRSS2 expression was strongly related with worse OS and FPS in LUAD, but not in LUSC, and decreased TMPRSS2 expression was obviously linked with OS and FPS in stage 1 lung cancer." (PMID 35017320, 2022). "The results indicated that TMPRSS2 had significantly lower protein expression in lung cancer." (PMID 35017320, 2022). "Some researchers have suggested that although patients with underlying diseases are more susceptible to SARS-CoV-2 infection, patients suffering from head and neck cancer or lung cancer have reduced expression of TMPRSS2 in the body, which makes these patients less susceptible to SARS-CoV-2." (PMID 35281819, 2022). "TMPRSS2 expression was significantly downregulated in lung cancer." (PMID 35017320, 2022). "In addition, the analysis results from the PrognoScan database indicated that decreased TMPRSS2 expression was linked with inferior OS and relapse-free survival (RFS) in different lung cancer cohort samples." (PMID 35017320, 2022). "Given that TMPRSS2 is a promising drug target for SARS-CoV-2, this study aimed to investigate the expression profile, determine the prognostic potential of TMPRSS2, and estimate the association between TMPRSS2 and immune cell infiltration in lung cancer." (PMID 35017320, 2022). "KEGG, GO and GSEA were performed to investigate the cellular function of TMPRSS2 in lung cancer." (PMID 35017320, 2022). "We conducted univariate Cox and multivariate Cox regression analyses to explore whether TMPRSS2 expression was an independent prognostic factor that correlated with the OS of lung cancer patients." (PMID 35017320, 2022). "We also evaluated the prognostic value of TMPRSS2 for lung cancer patients by performing Cox regression analyses and prognostic nomograms based on the correlation between TMPRSS2 expression and OS in lung cancer." (PMID 35017320, 2022). "cBioPortal was used to analyze the genetic alterations in TMPRSS2 in lung cancer." (PMID 35017320, 2022). "We also examined the protein expression level of TMPRSS2 in lung cancer using the UALCAN database." (PMID 35017320, 2022). "We also estimated whether TMPRSS2 influenced the prognosis of patients with lung cancer through its effects on immune cell infiltration." (PMID 35017320, 2022). "Therefore, we examined the prognosis of various immune infiltrating cells in breast cancer and lung cancer based on the TMPRSS2 expression level by the Kaplan-Meier plotter database." (PMID 35558557, 2022). "Considering the relationship between TMPRSS2 and the immune response, low TMPRSS2 expression in lung cancer patient tissues may lead to a decline in the immune function of patients with SARS-CoV-2 infection." (PMID 35017320, 2022). "Furthermore, the low TMPRSS2 expression predicted a short survival time in patients with lung cancer." (PMID 35017320, 2022). "In contrast to our speculation, TMPRSS2 expression in lung cancer tissues was generally downregulated." (PMID 35017320, 2022).
lung carcinoma (continued). "Genetic alterations in TMPRSS2 occurred in 1.2% of lung cancer patients." (PMID 35017320, 2022). "Previous studies have shown that ACE2 attenuated the metastasis of lung cancer and that TMPRSS2 fusion gene may induce resistance to EGFR-TKI, a standard first-line therapy for advanced NSCLC patients harboring EGFR mutation." (PMID 34094930, 2021). "RGS11 is associated with TMPRSS2-ERG fusion, and is a biomarker of lung cancer." (PMID 33498739, 2021). "The expression of ACE2 and TMPRSS2 in resection margin tissues, not tumors, of lung cancer survivors is more representative of the susceptibility to SARS-CoV-2." (PMID 34094930, 2021). "As ACE2 and TMPRSS2 are overexpressed in lung cancer, their expression may be high at the resection margin of lung cancer patients." (PMID 34094930, 2021). "In a lung cancer tissue array, it was found that distinct types of lung cancer are androgen receptor-positive, indicating that in addition to prostate tissues, androgen signaling also targets the lung to enhance the expression of TMPRSS2." (PMID 34001144, 2021). "The finding that ACE2 and TMPRSS2 are highly expressed in patients with lung cancer may be part of the reason why LUAD patients are more susceptible to SARS-CoV-2 infection." (PMID 33195212, 2020). "A very recent study by Kong (2020), analyzed the differential expression of ACE-2 and TMPRSS2 in two common types of lung cancers, lung adenocarcinoma (LUAD) and lung squamous cell carcinoma (LUSC), and their correlation with prognosis and SARS-CoV-2 infection." (PMID 32764454, 2020). "Collectively, these findings suggest that tumoral tissues, herein exemplified by HNSCC and lung cancers might be more resistant to SARS-CoV-2 infection due to reduced expression of TMPRSS2." (PMID 32967703, 2020). "These phenomena indicate that the mRNA expression level of TMPRSS2 could impact the clinicopathological parameters of lung cancer but the differences in prognosis patterns between LUAD and LUSC are less affected by the TMPRSS2-depended clinicopathological parameters." (PMID 36992839, 2023). "Moreover, the expression level of TMPRSS2 and the effector memory T-cell, resting Treg, T cell exhaustion, and effector Treg demonstrated different correlation patterns in the tumor tissue of lung cancer (AE, AA, AG)." (PMID 36992839, 2023). "Therefore, we investigated whether the expression of TMPRSS2 was correlated with immune infiltration levels in lung cancer." (PMID 36992839, 2023). "Therefore, we examined whether TMPRSS2 may be involved in the enhanced ability to promote tumor growth in lung cancer cells." (PMID 36975376, 2023). "Therefore, we speculated that the prognosis of lung cancer and breast cancer correlated with TMPRSS2 expression may be affected by the tumor immune infiltrating cells." (PMID 35558557, 2022). "Understanding TMPRSS2 expression in lung cancer patients and its relationship with prognosis may help clarify why cancer patients are more likely to be infected with SARS-CoV-2 and help determine whether lung cancer immunotherapy may change susceptibility to SARS-CoV-2 infection." (PMID 35017320, 2022). "However, whether TMPRSS2 is involved in regulating antitumor immunity and its clinical significance in lung cancer remain unknown." (PMID 35017320, 2022). "However, the expression of ACE2 and TMPRSS2 in resection margin tissues may be more valuable in medium-term lung cancer survivors." (PMID 34094930, 2021). "Similarly, TMPRSS2 shows the highest expression in colon, kidney and lung normal tissues (1st, 4th and 5th in rank) and consistently shows a significant different expression in colon, kidney and lung cancers." (PMID 32970391, 2020). "We then examined the kinetics of sgmRNA expression during Alpha infection of a human lung carcinoma cell line, A549, which stably expresses the SARS2-CoV-2 receptor and entry co-factor ACE2 and TMPRSS2 (AAT)." (PMID 39836705, 2025).
lung carcinoma (continued). "AhR nuclear expression also correlated with TMPRSS2 and IL18 expression and cancer stage in human lung cancer tissue." (PMID 37696458, 2023). "Since the TLR agonist poly (I: C) can enhance the expression of TMPRSS2 and act on innate immune cells, this means that the use of TLR agonists in lung cancer will enhance the efficacy of PD-1 targeting adaptive immune cells." (PMID 36992839, 2023). "Clinical correlation of TMPRSS2 expression with age, sex, nuclear AhR, IL18, and overall stage in 25 lung cancer patientsa." (PMID 36975376, 2023). "In the present study, we examined the expression of SARS-CoV-2 entry genes, including ACE2, TMPRSS2, CTSL, and AXL in primary human airway epithelial cells isolated from 11 lung cancer patients." (PMID 36148455, 2022). "As a suitable cell model, we chose human lung carcinoma A549 cells stably transfected with human ACE2 and TMPRSS2 (abbreviated: A549-AT)." (PMID 36015168, 2022). "We further compared the expression levels of CTSL, TMPRSS2, and FURIN in normal lungs and lung cancers." (PMID 35414771, 2022). "Intriguingly, we observed that TMPRSS2 expression correlated with infiltrating levels of CD8+ T cells, B cells, CD4+ T cells, neutrophils, macrophages, and dendritic cells in lung cancer." (PMID 35017320, 2022). "Compared to other proteases/proteinases/convertases such as TMPRSS2 and FURIN, the expression of CTSL was higher in both normal lungs and lung cancer samples." (PMID 35414771, 2022). "By further comparison of CTSL, TMPRSS2, and FURIN, all of which are proteinase/protease/convertases 43, 44, we found the expression of CTSL to be the highest in both in normal lungs and lung cancers." (PMID 35414771, 2022). "Since elevated levels of ACE2 and TMPRSS2 indicate a high susceptibility to SARS-CoV-2, and medium-term survivors did not have tumor burden, the expression of ACE2 and TMPRSS2 at resection margin tissue may indicate the susceptibility of lung cancer patients to SARS-CoV-2." (PMID 34094930, 2021). "Especially, five lung cancer-related genes including CYP4B1, CHRDL1, SFTPC, SFTPB, and AGER were consistently downregulated in both LUAD and LUSC had a positive correlation with TMPRSS2, exhibited an opposite effect on the prognosis of LUAD and LUSC." (PMID 35082790, 2021). "ACE2 barely shows any interaction in LUAD, LUSC, STAD or PRAD, but NRP1 and TMPRSS2 have multiple interactions in LUAD and LUSC, indicating significant roles of NRP1 and TEMPRSS2 in lung cancers." (PMID 34168096, 2021). "A recent investigation used the LungMAP website, GEPIA2 software and the lung cancer explorer (database consisting of 6700 patients) to analyze ACE-2 and TMPRSS2 expression in lung development and lung cancer, respectively." (PMID 32764454, 2020). "In HT-29 colorectal cancer cells and H1299 lung cancer cells, we observed that choloroquine and hydroxychloroquine increase expression of ACE2, TMPRSS2 and IL-6." (PMID 33245731, 2020). "In this study, we examined expression levels of ACE2, TMPRSS2, and cathepsin L in human airway epithelial cells derived from never smokers, former smokers, current smokers, patients with COPD, or lung cancer." (PMID 33425965, 2020). "In order for the virion to enter the target cell, the S protein must be primed by the cellular serine protease TMPRSS2, the inhibition of which has been demonstrated to limit SARS-CoV-2 infection of a human lung cancer cell line in vitro." (PMID 33312454, 2020). "The first to be discovered were in prostate cancer, where about half of all cases have the TMPRSS2-ERG fusion gene, and lung cancer, where around 5% of lung cancers have a fusion that activates the ALK tyrosine kinase, the EML4-ALK fusion." (PMID 23260012, 2012). "These preexisting conditions in lung cancer patients may result in heightened inflammation and diminish adaptive immune responses upon SARS‐CoV‐2 infection, highlighting the critical role of TMPRSS2 in immune modulation." (PMID 40145441, 2025).
lung carcinoma (continued). "That is, the level of TMPRSS2 expression and methylation are basically the same in the two lung cancer subtypes, so we believe that the difference between TMPRSS2 on LUAD and LUSC prognosis was also not at the methylation level." (PMID 36992839, 2023). "To evaluate the relationship between TMPRSS2 and immune infiltrating cells, we focused on the correlations between TMPRSS2 and immune cells, including general T cells, CD8+ T cells, Treg, M2 macrophages, monocyte, and DC in tumor and normal tissue of lung cancer." (PMID 36992839, 2023). "In addition, colorectal cancer and lung cancer tissues highly express ACE2 and TMPRSS2 resulting in severe symptoms and/or unfavorable prognosis of SARS-CoV-2 infection." (PMID 37142998, 2023). "For a greater understanding of the correlation and mechanism of TMPRSS2 expression level in LUAD and LUSC, we further studied the correlation between TMPRSS2 expression and clinical prognosis in patients with lung cancer with various clinicopathological factors." (PMID 36992839, 2023). "Additionally, KEGG analysis results suggested that TMPRSS2 was involved in adrenergic signaling in cardiomyocytes, ECM-receptor interaction, hypertrophic cardiomyopathy (HCM), and bile secretion in lung cancer." (PMID 35017320, 2022). "Moreover, there was a significant correlation between TMPRSS2 expression and the infiltration abundances of CD8+ T cells, CD4+ T cells, B cells, neutrophils, macrophages, and dendritic cells in lung cancer." (PMID 35017320, 2022). "Finally, we evaluated fluoxetine effectiveness in the human A549 lung carcinoma cells stably overexpressing the SARS-CoV-2 receptor ACE2, and the protease TMPRSS2 to increase their permissiveness to SARS-CoV-2 infection." (PMID 36362409, 2022). "We observed that TMPRSS2 expression was decreased in lung cancer tissues compared with adjacent nontumor tissues." (PMID 35017320, 2022). "We also explored the differences in the expression of ACE2 and TMPRSS2 in resection margin tissues of lung cancer patients and normal lung tissues of non-cancerous patients." (PMID 34094930, 2021). "The expression of ACE2 (P = 0.013) and TMPRSS2 (P <0.001) was elevated in lung cancer survivors as compared with that in non-cancer individuals." (PMID 34094930, 2021). "In addition to its excellent TMPRSS2 inhibition, PK, and antiviral activity, VD2173 has anticancer efficacy in animal models of lung cancer." (PMID 34635581, 2021). "We further explored the prognostic impact of TMPRSS2 expression and immune infiltration in LUAD and LUSC, we studied the relationship between different immune cells and lung cancer OS, and the relationship between the combined effect of TMPRSS2 and immune cells and lung cancer OS respectively." (PMID 36992839, 2023). "In addition, both our study and previous studies believed that TMPRSS2 as a cancer suppressor gene was significantly down‐regulated in two types of tumour tissues of LUAD and LUSC, the expression of TMPRSS2 have an impact on the prognosis of lung cancer." (PMID 34951103, 2022). "Normal lung tissues exhibited moderate TMPRSS2 staining, while TMPRSS2 could not be detected in most lung cancer tissues." (PMID 35017320, 2022). "Conclusively, the results implicate that quinine exhibits antiviral activity against SARS-CoV-2 in A549 lung cancer cell lines and that its antiviral activity might be modulated but not abrogated by the expression of TMPRSS2." (PMID 33918670, 2021). "furin mRNA levels were 49.56-fold higher than that of ACE2 in lung normal tissues and 4-fold higher in lung cancer tissues, implying that SARS-CoV-2 might not only use TMPRSS2 or ACE2 to attack tissues from normal and cancerous organ tissues, but also use furin, particularly in lung cancer tissues." (PMID 34671211, 2021).